FSD1 (fibronectin type III and SPRY domain containing 1)
Description:
May be involved in microtubule organization and stabilization.
Synonyms: GLFND; MIR1; MGC3213
Tractability: PROTAC: ubiquitination databases record sites on it; its protein half-life has been measured.
Gene: Protein-coding gene on chromosome 19 (4,304,595 to 4,323,843, forward strand). Ensembl gene ENSG00000105255.
Subcellular location: Cytoplasm, cytoskeleton, microtubule organizing center, centrosome; Nucleus; Cytoplasm; Cleavage furrow
Subcellular location (Human Protein Atlas): Cytosol
Gene Ontology:
Molecular function: identical protein binding; microtubule binding
Biological process: cytoplasmic microtubule organization; regulation of cell division; regulation of cytokinesis; regulation of mitotic spindle organization
Cellular component: centrosome; cytosol; microtubule; cleavage furrow; cytoplasm; nucleus
Genetic constraint (gnomAD): Loss-of-function variants: 21 observed, 53.23 expected, observed/expected ratio (o/e) 0.39, 90% interval 0.28 to 0.57. The upper end of that interval is the gene's LOEUF score, 0.57, which puts it in group 2 of 6, group 1 being the genes least tolerant of losing a copy. Missense variants: 523 observed, 642.1 expected, observed/expected ratio (o/e) 0.81, 90% interval 0.76 to 0.88. Synonymous variants: 249 observed, 256.28 expected, observed/expected ratio (o/e) 0.97, 90% interval 0.88 to 1.08.
Homologues: Orthologues: chimpanzee FSD1 (100% identical), dog FSD1 (96% identical), pig FSD1 (96% identical), guinea pig FSD1 (95% identical), mouse Fsd1 (93% identical), macaque FSD1 (92% identical), rat Fsd1 (92% identical), tropical clawed frog fsd1 (71% identical), zebrafish fsd1 (69% identical), rabbit FSD1 (59% identical). Paralogues in human: FSD1L (60% identical), CMYA5 (23% identical), FSD2 (21% identical).
Diseases named in the same sentence as FSD1 in open-access papers:
FSD1 is named in the same sentence as 1 disease in open-access papers, as found by Europe PMC text mining. Sharing a sentence is not in itself a finding about the gene and the disease. The quoted sentences say what the papers report.
viral infection (1 paper, 2022). "These four molecules are characteristic of each subtype, including: SEZ6 for autoimmune subtype, SPOCK3 for inflammation, FSD1 for viral infection, and PGC for oxidative stress." (PMID 36713418, 2022).